CCDC138 (coiled-coil domain containing 138)
Synonyms: FLJ32745
Tractability: PROTAC: ubiquitination databases record sites on it.
Gene: Protein-coding gene on chromosome 2 (108,786,745 to 108,885,477, forward strand). Ensembl gene ENSG00000163006.
Subcellular location (Human Protein Atlas): Nucleoplasm; Cytosol
Genetic constraint (gnomAD): Loss-of-function variants: 34 observed, 49.49 expected, observed/expected ratio (o/e) 0.69, 90% interval 0.52 to 0.92. The upper end of that interval is the gene's LOEUF score, 0.92, which puts it in group 3 of 6, group 1 being the genes least tolerant of losing a copy. Missense variants: 553 observed, 530.8 expected, observed/expected ratio (o/e) 1.04, 90% interval 0.97 to 1.12. Synonymous variants: 213 observed, 188.17 expected, observed/expected ratio (o/e) 1.13, 90% interval 1.01 to 1.27.
Homologues: Orthologues: chimpanzee CCDC138 (99% identical), macaque CCDC138 (98% identical), rabbit CCDC138 (85% identical), rat Ccdc138 (81% identical), pig CCDC138 (80% identical), guinea pig CCDC138 (79% identical), mouse Ccdc138 (79% identical), dog CCDC138 (75% identical), tropical clawed frog ccdc138 (44% identical).
Diseases named in the same sentence as CCDC138 in open-access papers:
CCDC138 is named in the same sentence as 7 diseases in open-access papers, as found by Europe PMC text mining. Sharing a sentence is not in itself a finding about the gene and the disease. The quoted sentences say what the papers report.
ciliopathies (2 papers, 2017 to 2025). "As a ciliopathy-associated gene, CCDC138 bridges ciliary dysfunction and cancer, offering a novel biomarker and therapeutic target for precision oncology in UCEC." (PMID 40861419, 2025). "While coiled-coil domain-containing protein 138 (CCDC138) is implicated in ciliopathies and cancer, its role in UCEC remains underexplored." (PMID 40861419, 2025). "As a ciliopathy-associated gene, CCDC138 may influence the structure and function of primary cilia—organelles essential for signal transduction, cellular differentiation, proliferation, and tissue homeostasis." (PMID 40861419, 2025). "As a gene implicated in ciliopathies and UCEC, CCDC138 offers a novel perspective for exploring the molecular link between ciliary dysfunction and cancer." (PMID 40861419, 2025). "Third, the study did not directly assess the role of CCDC138 in ciliary function, which would further clarify its role in ciliopathies and tumor biology." (PMID 40861419, 2025).
epidermoid carcinoma (1 paper, 2025). "Immunofluorescence analysis of A-431 (epidermoid carcinoma), U-251MG (glioma), and U-2 OS (osteosarcoma) cell lines, as reported in the THPA, was used to investigate the subcellular distribution of CCDC138." (PMID 40861419, 2025).
cancer (1 paper, 2025). A tumor composed of atypical neoplastic, often pleomorphic cells that invade other tissues. "For example, alpelisib targets the PI3K pathway and has shown clinical efficacy in various cancers; CCDC138 expression may help identify patients with UCEC likely to benefit from such targeted therapies." (PMID 40861419, 2025). "Through these interactions, CCDC138 may influence both cancer progression and ciliary dysfunction, reinforcing its relevance in both disease contexts." (PMID 40861419, 2025). "CCDC138 was significantly upregulated in several cancers, including UCEC." (PMID 40861419, 2025). "Coiled-coil domain-containing protein 138 (CCDC138), known for its role in ciliogenesis, has recently gained attention due to its involvement in cancer." (PMID 40861419, 2025). "Further analysis using the TIMER database confirmed negative associations between CCDC138 expression and immune cell infiltration, significant links with OS in patients with UCEC, and the highest CCDC138 mutation frequency among TCGA cancer types." (PMID 40861419, 2025).
tumor (1 paper, 2025). "We focused on CCDC138 to examine its expression patterns, prognostic value, association with oncogenic and cilia-related pathways, immune cell infiltration, tumor microenvironment (TME) regulation, and drug sensitivity." (PMID 40861419, 2025). "The results also showed that high CCDC138 expression was associated with lower immune and stromal scores, and higher tumor purity, indicative of an immunosuppressive TME." (PMID 40861419, 2025). "High CCDC138 expression was linked to reduced stromal and immune scores, indicating altered immune cell infiltration and tumor microenvironment." (PMID 40861419, 2025). "Differential expression analysis further revealed that CCDC138 expression was significantly elevated in UCEC tumor tissues compared to that in normal tissues, highlighting its potential as a prognostic biomarker." (PMID 40861419, 2025). "Protein-level analysis using the CPTAC dataset via the UALCAN portal further confirmed elevated CCDC138 expression in UCEC tumor tissues compared to that in normal controls (31 normal vs. 100 tumor samples)." (PMID 40861419, 2025). "In vitro validation further supported this, as CCDC138 knockdown significantly reduced proliferation rates (53.44% vs. 62.90% at 24 h, 84.51% vs. 106.32% at 48 h, 110.26% vs. 150.36% at 72 h), indicating a direct role in driving tumor cell growth." (PMID 40861419, 2025). "The high CCDC138 expression group exhibited significantly lower stromal scores (p = 3.92e-07) and immune scores (p = 1.41e-08), with higher tumor purity (p = 1.88e-10), indicating that CCDC138 may influence the TME and contribute to tumor progression." (PMID 40861419, 2025). "The overexpression of CCDC138 across UCEC subtypes, stages, and grades suggests its involvement in tumor development and progression." (PMID 40861419, 2025).
CCDC138 also shares sentences with these, for which no sentence is quoted: glioma (1 paper); osteosarcoma (1); uterine corpus endometrial carcinoma (1).